TMEM126B (transmembrane protein 126B)
Description:
As part of the MCIA complex, involved in the assembly of the mitochondrial complex I. Participates in constructing the membrane arm of complex I.
Synonyms: HT007; MC1DN29
Tractability: Antibody: UniProt predicts a signal peptide or a membrane-spanning region. PROTAC: ubiquitination databases record sites on it; its protein half-life has been measured.
Gene: Protein-coding gene on chromosome 11 (85,628,573 to 85,636,539, forward strand). Ensembl gene ENSG00000171204.
Subcellular location: Mitochondrion membrane
Subcellular location (Human Protein Atlas): Mitochondria
Pathways (Reactome):
Metabolism: Complex I biogenesis
Gene Ontology:
Molecular function: protein binding
Biological process: mitochondrial respiratory chain complex I assembly
Cellular component: mitochondrial complex I intermediate assembly complex; mitochondrial membrane; mitochondrion; mitochondrial inner membrane
Genetic constraint (gnomAD): Loss-of-function variants: 19 observed, 14.56 expected, observed/expected ratio (o/e) 1.3, 90% interval 0.91 to 1.83. The upper end of that interval is the gene's LOEUF score, 1.83, which puts it in group 6 of 6, group 1 being the genes least tolerant of losing a copy. Missense variants: 289 observed, 278.45 expected, observed/expected ratio (o/e) 1.04, 90% interval 0.94 to 1.14. Synonymous variants: 102 observed, 91.93 expected, observed/expected ratio (o/e) 1.11, 90% interval 0.94 to 1.31.
Gene-disease validity (ClinGen):
ClinGen rates the evidence that TMEM126B causes each of these diseases.
mitochondrial disease (autosomal recessive): Definitive.
Homologues: Orthologues: chimpanzee TMEM126B (99% identical), macaque TMEM126B (90% identical), pig TMEM126B (67% identical), guinea pig TMEM126B (59% identical), rat Tmem126b (57% identical), mouse Tmem126b (55% identical), dog TMEM126B (51% identical), tropical clawed frog tmem126a (27% identical), zebrafish tmem126a (22% identical), Drosophila melanogaster CG13392 (15% identical). Paralogues in human: TMEM126A (24% identical).
Diseases named in the same sentence as TMEM126B in open-access papers:
TMEM126B is named in the same sentence as 6 diseases in open-access papers, as found by Europe PMC text mining. Sharing a sentence is not in itself a finding about the gene and the disease. The quoted sentences say what the papers report.
cardiomyopathy (3 papers, 2016 to 2023). A disease of the heart muscle or myocardium proper. "As shown, individuals carrying TMEM126B mutations mainly presented with exercise intolerance, muscle weakness, hyperlactic acidemia, pure myopathy, chronic renal failure and cardiomyopathy." (PMID 36482121, 2023). "Notably, the clinical phenotypes of our patient are consistent with those of patients carrying TMEM126B mutations previously reported, except for chronic renal failure and cardiomyopathy." (PMID 36482121, 2023). "Twelve of the 52 mouse models identified with cardiomyopathy (Acadv1, Fxn, Mto1, Taco1, Hmgcs2, Mpv17, Opa1, Pnpla8, Tmem126b, Gpd2, Mpv17, Micu1) showed that the presence of cardiomyopathy can be dependent on the degree of stress." (PMID 37103033, 2023).
atherosclerosis (1 paper, 2024). A disease characterized by the build-up of fatty material and calcium deposition in the arterial wall resulting in partial or complete occlusion of the arterial lumen. "Mitochondrial and metabolism-related genes such as NDUFS7, TMEM126B, and EIF3G were clustered together, indicating a metabolic impairment in atherosclerosis." (PMID 39120300, 2024).
mitochondrial disease (2 papers, 2016 to 2023). "The combination of clinical and molecular diagnosis are required for the diagnosis of TMEM126B mutation‐related mitochondrial diseases." (PMID 36482121, 2023). "Our study not only expands the genetic mutation spectrum of LLS but the clinical spectrum caused by TMEM126B mutations, thus contributing to the clinical diagnosis of TMEM126B mutation-related mitochondrial diseases." (PMID 36482121, 2023). "Here, we describe the clinical, biochemical, and molecular findings in six cases of mitochondrial disease from four unrelated families affected by biallelic (c.635G>T [p.Gly212Val] and/or c.401delA [p.Asn134Ilefs∗2]) TMEM126B variants." (PMID 27374774, 2016). "Characterization of TMEM126B after proteomic screening and subsequent application of diagnostic MPS strategies has resulted in the diagnosis of six subjects from four families affected by TMEM126B-related mitochondrial disease." (PMID 27374774, 2016).
myopathy (2 papers, 2016 to 2023). A disease of the muscle in which the muscle fibers do not function properly. "Five of the six subjects have relatively mild symptoms, confined mostly to myopathy, and all have normal cognitive development despite having a severe complex I defect in muscle and the fact that TMEM126B appears to be a ubiquitous complex I assembly factor." (PMID 27374774, 2016).
TMEM126B also shares sentences with these, for which no sentence is quoted: chronic renal failure (2 papers); COVID-19 (1).